DAB2 (DAB adaptor protein 2)
Diseases named in the same sentence as DAB2 in open-access papers (continued):
Sharing a sentence is not in itself a finding about the gene and the disease.
ovarian carcinoma (continued). "In this study, we reported DAB2 expression was significantly reduced in ovarian cancer compared to normal OSE, consistent with previous ovarian cancer studies." (PMID 37815603, 2023). "The relationship between DAB2 expression and macrophages was confirmed in the TIMER dataset, which examines immune infiltrates in ovarian cancer tissues in the TCGA dataset." (PMID 37815603, 2023). "Using the GENT2 database, we analysed DAB2 expression in normal tissues (OSE and FT) and ovarian cancer tissues." (PMID 37815603, 2023). "We observed strong positive correlations between DAB2 and EMT markers in online database analysis of ovarian cancer cell lines and patient tissues." (PMID 37815603, 2023). "DAB2 expression had significant positive correlations with mesenchymal markers (ZEB2, TGFβ1, SNAI2, ZEB1, FN1, MMP2, TWIST1 and MMP3) and CSC markers (CD44 and MYD88) in ovarian cancer cell lines (CCLE) and tissues (TCGA: RNA sequencing and microarray)." (PMID 37815603, 2023). "DAB2 expression had a significant positive correlation with HA synthesis protein HAS2, HA receptor CD44 and co-receptor toll like receptor 4 (TLR4) in both ovarian cancer cell lines (CCLE) and patient tissues (TCGA: microarray and RNAsequencing data)." (PMID 37815603, 2023). "Furthermore, DAB2 promotes EMT and enhances cell migration and proliferation in ovarian cancer and urothelial carcinoma of the bladder, and FSCN1 can positively regulate EMT and extracellular matrix disassembly." (PMID 36176992, 2022). "DAB2 was also named DOC-2, which is differentially expressed in human ovarian carcinoma cells." (PMID 32607799, 2020). "DAB2 is expressed in normal ovarian epithelial cells but is downregulated or absent from ovarian carcinoma cell lines, suggesting its role as a tumor suppressor." (PMID 25861644, 2015). "Dab2 was also found lost in ovarian cancer, correlating with the absence of GATA6 and morphological transformation." (PMID 19649254, 2009). "It interacts directly with the DOC-2/DAB2 (also known as differentially expressed in ovarian carcinoma-2, DOC-2) protein that appears to be a tumour suppressor in malignant tumours, including mammary, prostate and ovarian cancers." (PMID 15770214, 2005). "DAB2 may also have a tumor suppressor role as it is normally expressed in ovarian epithelial cells but downregulated or absent in ovarian cancer cell lines." (PMID 37686244, 2023). "The link of Dab2 to oncogenesis was first made in a differential expression screening experiment, in which a short mRNA fragment was identified as DOC-2 (differentially expressed in ovarian cancer, known as Dab2 at a later time), and the mRNA was found lost in ovarian cancer." (PMID 27933291, 2016). "Given that DAB2 is highly expressed in healthy human OSE and is absent in the majority of ovarian tumours, this study has taken the first steps to provide a mechanistic explanation for how estrogen therapy may play a role in the initiation of ovarian cancer." (PMID 29196616, 2017).
breast cancer (27 papers, 2006 to 2023). A primary or metastatic malignant neoplasm involving the breast. "Downregulation of DAB2 significantly increases the association of SOS with Grb2 in M1 breast cancer cells, enhancing ERK phosphorylation and activating TGFβ signaling mediated EMT." (PMID 37815603, 2023). "DAB2 knockdown in tumor associated macrophages (TAMs) has been found to reduce lung metastases of E0771 breast cancer cells in vivo." (PMID 37815603, 2023). "According to previous literatures, promoter hypermethylation of DAB2 associated with the loss expression of DAB2 in many types of human cancers, such as nasopharyngeal carcinoma, breast cancer, and esophageal squamous cell carcinomas." (PMID 37223105, 2022). "Another study in breast cancer found only 11% of patients had hypermethylation of the DAB2 promoter despite 74% of patients exhibiting loss of DAB2 expression." (PMID 36614139, 2022). "Loss of the DAB2 p96 isoform was observed in breast cancer, but low expression of the p67 isoform was observed in both normal and cancerous breast tissue." (PMID 36614139, 2022). "Pervious study reported that, loss of DAB2 expression induced immune tolerance via accumulation of TGF-β in breast cancer." (PMID 37223105, 2022). "Follow up studies corroborated the loss of Dab2 expression in ovarian and breast cancer and its cell growth suppressive activity, and substantiated the proposal for Dab2 as a tumor suppressor." (PMID 27933291, 2016). "Subsequently, loss or reduction of Dab2 expression was found in other cancer types including rat mammary tumors, breast cancer, colon cancer, esophageal cancer, urothelial carcinomas, prostate cancer, head and neck cancer, and nasopharyngeal carcinomas." (PMID 24168030, 2013). "Several subsequent reports corroborated loss or a reduced Dab2 expression in human breast cancer." (PMID 27933291, 2016). "Loss of Dab2 expression, commonly observed in breast cancer, may facilitate TGFβ-stimulated EMT, and therefore increase the propensity for metastasis." (PMID 21063401, 2010). "Although not determined in this study, it is tempting to speculate that Dab2 promoter hypermethylation is associated with a specific subtype of breast cancer, the basal subtype, as these tumours have been shown to specifically exhibit an EMT-like phenotype." (PMID 21063401, 2010). "Thus, the induction of Dab2 expression may contribute to the protection against breast cancer risk that pregnancy and lactation may offer." (PMID 27933291, 2016). "This work revealed a critical result that breast cancer cell was deficient in Dab2 expression and related receptor endocytosis-mediated TGF-β depletion, which may contribute to the accumulation of TGF-β in tumor microenvironment and the induction of immune tolerance." (PMID 24638085, 2014). "Loss of Dab2 expression may thus supply activation of the Ras pathway in breast cancer, which along with other genetic changes, leads to the development of the aggressive and basal subtype of breast cancer." (PMID 21063401, 2010). "This is consistent with other studies in acute myeloid leukaemia, breast cancer, lung, and hepatocellular cancers where DAB2 inhibited cell proliferation." (PMID 37815603, 2023). "Inhibiting miR-191 expression in ER+ breast cancer, enhanced DAB2 expression and reduced tumorigenesis in vivo." (PMID 36614139, 2022). "DAB2 was highly expressed in TAMs and its knockdown significantly reduced lung metastasis in mouse fibrosarcoma and breast cancer models." (PMID 36614139, 2022). "Oestrogen-induced cell proliferation was associated with increased miR-191 expression and the silencing of DAB2 expression in oestrogen receptor (ER) positive breast cancer cell lines." (PMID 36614139, 2022). "DAB2 KD in myeloid cells significantly reduced the invasiveness of E0771 breast cancer cells in vitro as well as number of lung metastases in vivo." (PMID 36614139, 2022).
breast cancer (continued). "Restoration of Dab2 expression in SK-BR-3 breast cancer cells was shown to promote TGFβ depletion from the surrounding media through receptor trafficking; and these decreased TGFβ levels inhibited production of regulatory T cells (Tregs) from naïve T cells." (PMID 31101868, 2019). "An interest to examine a potential role of Dab2 in mammary glands was prompted by the findings that Dab2 expression is lost in breast cancer and in carcinogen-induced rodent mammary tumors." (PMID 27933291, 2016). "Another early support was the identification of Dab2 as a suppressed gene in carcinogen-induced mammary tumors in rodents." (PMID 27933291, 2016). "Levels of Dab2 protein expression in all three breast cancer cell lines were reduced significantly, compared to normal breast epithelial cells (MCF-10A; the positive control)." (PMID 24638085, 2014). "Furthermore, post-lactational involution may purge pre-neoplastic cells, but dysregulation of the process could facilitate tumor formation Our finding suggests that Dab2 may be one of the genes involved in providing a protective effect for pregnancy against breast cancer risk." (PMID 25360623, 2014). "The expression of Dab2 in three breast cancer cell lines (MCF-7, MDA-MB-231, and SK-BR-3) was analyzed with the western blotting assay." (PMID 24638085, 2014). "Dab2 expression is lost in several cancer types including breast cancer, and Dab2 is thought to have a tumor suppressor function." (PMID 25360623, 2014). "DAB2 expression is also reduced in breast cancer, which results in up-regulation of TGFβ2 that promotes EMT transition." (PMID 23213280, 2012). "Previous studies suggested that DNA methylation in the promoter region of DAB2 is infrequent in esophageal and breast cancers." (PMID 20525238, 2010). "To study the role of Dab2 in breast cancer progression, we have utilised two normal mammary epithelial cell lines MCF10A1 and HME5-cdk4." (PMID 21063401, 2010). "To further extend these observations, we probed the relative mRNA abundance of the p96 and p67 isoforms of Dab2 in 12 normal human breast tissue and 12 breast cancer samples using the Human Breast Cancer Rapid-Scan Panel (Origene)." (PMID 21063401, 2010). "In our study, we have downregulated Dab2 expression utilising shRNA-mediated technology; however, the mechanism whereby Dab2 expression is decreased in the course of breast cancer development remains undetermined." (PMID 21063401, 2010). "Comparison of genes differentially expressed in an in vivo mouse mammary carcinogenesis model indicated that Dab2 was downregulated in 80% of mammary tumours." (PMID 21063401, 2010). "In conclusion, we show here that downregulation of Dab2, which is commonly observed in breast cancer, can lead to enhanced Ras/MAPK signalling, increased expression of TGFβ2 and constitutive EMT." (PMID 21063401, 2010). "MCF10A1 and HME5-cdk4 cells thus provide a relevant model system to study the effects of Dab2 downregulation early in breast cancer development." (PMID 21063401, 2010). "Disabled-2 (Dab2) is a putative tumour suppressor whose expression has been shown to be downregulated in various cancer types including breast cancer; however, its exact function in suppressing tumour initiation or progression is unclear." (PMID 21063401, 2010). "A closer look at the eight Ox-E/ER genes linked to these growth factors revealed that most (EGR1, PHLDA1, IGFBP5, TAGLN, DAB2, and FHL2) have been associated with breast cancer." (PMID 18631401, 2008). "Thus, it has been shown that activation of miR-191/DAB2 axis is crucial in estrogen-induced ER+ breast cancer growth." (PMID 36555323, 2022). "DAB2 has also been implicated as a negative regulator of myosin VI nuclear activity, such as the transcription of oestrogen receptor (ER) target genes in MCF-7 breast cancer cells." (PMID 36614139, 2022).
breast cancer (continued). "miR-191 promotes cellular viability of estrogen-dependent breast cancer cells by directly suppressing the expression of DAB2 and might play a critical role in estrogen signaling pathway in the development and progression of ER + breast cancer." (PMID 35096064, 2022). "Furthermore, the analysis of aberrant hypermethylation of Dab2 promotor were performed in Nasopharyngeal carcinomas, Esophageal Squamous Cell Cancers, breast cancers and lung cancers, respectively." (PMID 24772157, 2014). "Dab2 expression is often lost in cancers, including breast cancer." (PMID 25360623, 2014). "Taken together, our findings indicated that Dab2 was largely lost in breast cancer cells." (PMID 24638085, 2014). "Moreover, Dab2 was identified as a down regulated gene in carcinogen-induced mammary tumors in rodents, providing the first link between Dab2 and breast cancer." (PMID 25360623, 2014). "Several subsequent studies confirmed a reduced Dab2 expression in human breast cancer." (PMID 25360623, 2014). "Although decreased Dab2 mRNA levels were observed in all human breast cancer samples analyzed, irrespective of tumour grade, the decreased expression of Dab2 in the DCIS sample suggests that Dab2 loss occurs early in breast cancer progression." (PMID 21063401, 2010). "Although we cannot ascertain that the normal mammary tissue utilised in this study contains equal amounts of epithelial cells, the data presented here suggest that downregulation of both the p96 and p67 isoforms of Dab2 occurs frequently during breast cancer progression." (PMID 21063401, 2010). "To examine the role of Dab2 as a tumour suppressor in breast cancer, we chose to stably downregulate Dab2 expression utilising shRNA-mediated technology in the normal human mammary epithelial cell line MCF10A1, which harbours a defective p16/INK4a locus allowing for continued cell growth." (PMID 21063401, 2010). "DAB2 inhibition of ERK1/2 and c-Fos was confirmed in ovarian (OVCAR3, PA-1) and breast cancer cell lines (MCF-10, SK-Br-2 and MCF-7)." (PMID 36614139, 2022). "This phenomenon was also independently observed in an ESR1-positive human breast cancer cell line where microarray data comparing control and ESR1 siRNA transfected MCF7 cells showed that knockdown of ESR1 significantly increased DAB2 expression." (PMID 29196616, 2017). "miR-93-5p has been demonstrated to directly target DAB2 to promote cell migration and invasion in prostate cancer 23, and it can also regulate cell migration and invasion by suppressing PTEN through the PI3K/Akt pathway in breast cancer." (PMID 32328191, 2020). "Finally, we have demonstrated that E2 suppression of Dab2 occurs both in vivo and in vitro, and across many cell types including mouse FTE and human ovarian and breast cancer cells." (PMID 29196616, 2017). "Dab2 exerts its role in directional endocytic transport and epithelial organization, and transfection of Dab2 into ovarian and breast cancer cells lacking Dab2 expression restored the requirement of adhesion to basement membranes." (PMID 25360623, 2014). "Despite of years of intensive studies, the role of Dab2 down-regulation in the development and progression of breast cancer is not fully defined." (PMID 24638085, 2014). "Indeed, MDA-MB 231 cells, a metastatic basal-like breast cancer cell line, which expresses EMT markers, exhibits Dab2 promoter hypermethylation." (PMID 21063401, 2010). "Additionally, Dab2 was not inducible by estrogen and progesterone in primary mammary epithelial cells isolated from virgin mice, human breast epithelial cells, or estrogen-dependent breast cancer cells (such as MCF-7)." (PMID 25360623, 2014). "DAB2, MMP14, and SPP1 were also consistently expressed in CD68+ microglia/macrophages in patient-derived breast cancer BrM (n = 4), while their expression was absent from the patient-matched blood." (PMID 31501884, 2020).
lung carcinoma (14 papers, 2012 to 2024). "In lung cancer, low DAB2 protein expression was associated with reduced OS, reduced progression free survival (PFS), higher tumour stage and metastasis." (PMID 36614139, 2022). "In lung cancer DAB2 downregulation was associated with promoter methylation." (PMID 37815603, 2023). "miR-134-5p could silence DAB2 expression and was associated with reduced E-cadherin expression and enhanced migration, invasion, in vivo metastasis and resistance to cisplatin in lung cancer cell lines." (PMID 36614139, 2022). "Previous studies in bladder and lung cancer have found DAB2 expression was downregulated in metastatic tumors compared to primary tumors." (PMID 37815603, 2023). "Approximately 25% of lung cancer patients had high DAB2 tumour expression compared to 56% in normal lung tissues." (PMID 36614139, 2022). "This is also relevant in lung cancer where DAB2 expression has been suggested as a marker for epithelioid mesothelioma which has 80–98% DAB2 positivity compared to 3–23% for pulmonary adenocarcinoma cases." (PMID 36614139, 2022). "Based on the role of miR-93 in enhancing the malignancy of lung cancer cells, this miR downregulates the expression of DAB2 to promote the proliferation and malignancy of these tumor cells." (PMID 32612456, 2020). "The miR-93-directed down-regulation of DAB2 was shown to be the most important element that contributed to lung cancer tumorigenesis." (PMID 32025216, 2020). "MiR-93 regulates translocation of liposarcoma 1 (TLS1, FUS1), transducin repeat containing 2 (TRCP2), and disabled homolog 2 (DAB2), and plays an oncogenic role in lung cancer carcinogenesis." (PMID 32426273, 2020). "We previously reported that the Wnt signaling pathway is abnormally activated in lung cancer due to decreased expression of Dab2 and Axin, which inhibits the degradation of β-catenin resulting in its accumulation in the cytoplasm and nucleus." (PMID 30547821, 2018). "X-ray treatment significantly inhibits proliferation and invasion of lung cancer cells with hypermethylation of the Dab2 gene promoter, but is less effective in lung cancer cells with hypomethylation of the Dab2 gene promoter." (PMID 30547821, 2018). "Dab2 or Axin knockdown significantly decreased the ability of X-ray irradiation to reduce the proliferative activity of lung cancer cells." (PMID 30547821, 2018). "Immunostaining was performed to investigate the relationship between Dab2 expression and lung cancer clinicopathological characteristics." (PMID 30547821, 2018). "The result of immunostaining of Dab2 in lung cancer tissues showed that decreased Dab2 expression was positively correlated with poor differentiation, lymph node metastasis, advanced TNM stage and poor prognosis." (PMID 30547821, 2018). "We previously reported that Dab2 was down-regulated due to gene promoter hypermethylation in lung cancer." (PMID 30547821, 2018). "We also have previously found that hypermethylation of the Dab2 gene promoter was correlated with reduced expression in lung cancer." (PMID 30547821, 2018). "We thus examined the correlation between TC1 and other Wnt pathway members including β-catenin, Chibby, TCF4, Axin, and Dab2 in lung cancers." (PMID 28968956, 2017). "Along with the examination of TC1, expression levels of DNMT1, β-catenin, TCF4, Axin, Dab2, and Chibby were also examined in 84 lung cancer specimens." (PMID 28968956, 2017). "Studies showed that DAB2 protein as a tumor suppressor inhibits cell growth in lung cancer, and miR-93, which is homologous to miR-106b, can inhibit its function in regulating the DAB2 protein level." (PMID 26769181, 2016). "DAB2 is underexpressed in tumors compared to normal tissue and correlates with the malignant phenotype of lung cancer, urothelial carcinoma, squamous cell carcinoma, nasopharyngeal carcinoma, and esophageal squamous carcinoma." (PMID 23213280, 2012). "The expression of DAB2 undergoes down-regulation in various cancers and lung cancer is among them." (PMID 32612456, 2020).